TRPV4 (transient receptor potential cation channel subfamily V member 4)
Diseases named in the same sentence as TRPV4 in open-access papers (continued):
Sharing a sentence is not in itself a finding about the gene and the disease.
glioma (continued). "In this study, we have shown that the actin-bundling protein TRPV4 is expressed in normal brain tissues, glioma tissues and permanent glioblastoma cell lines." (PMID 32843668, 2020). "In contrast, strong TRPV4 staining was observed in the cytoplasm and membrane of high-grade glioma (HGG, WHO III and IV)." (PMID 32843668, 2020). "The results showed weak TRPV4 staining in normal brain tissues (control), and TRPV4 was predominantly observed in the membrane and cytoplasm of tumor cells of low-grade glioma (LGG, WHOI and II)." (PMID 32843668, 2020). "For instance, mRNA encoding TRPC1, TRPC6, TRPM7, TRPM8, TRPV4, and TRPML2 appeared up-regulated in GBM tumor specimens in comparison with normal tissues and their expression was found to increase with glioma tumor grade with the highest mRNA level found in GBM patient samples." (PMID 33928077, 2021). "Furthermore, Ou Yang-and colleagues proposed that TRPV4 accelerated glioma migration and invasion and served as a potential target for glioma therapy." (PMID 34814869, 2021). "Similarly to TRPM8, TRPV4 has been shown to positively correlate with glioma progression, since high levels of TRPV4 gene and protein expression were associated with a poorer patient prognosis." (PMID 33928077, 2021). "Conversely to TRPV1 and TRPV2, TRPV4 has revealed a pivotal role in promoting glioma progression." (PMID 33928077, 2021). "TRPV4 expression level was negatively correlated with prognosis in patients with all grades of glioma and glioblastoma multiforme thus, we concluded that TRPV4 could be a biomarker and prognostic factor for glioblastoma patients." (PMID 32843668, 2020). "To investigate whether TRPV4 is a biomarker for glioma, we first detected the expression of TRPV4 in normal brain tissues and different grades of glioma by IHC assays." (PMID 32843668, 2020). "Thus, TRPM8 and TRPV4 may be currently considered promising biomarkers accompanying aggressiveness of glioma and signature of GBM while constituting potential therapeutic targets for future treatment options." (PMID 33928077, 2021). "Interestingly, TRPV4 expression increased with the malignancy grade of glioma." (PMID 32843668, 2020). "MCOLN2, TRPV4, and ITPR2 were significantly highly expressed in glioma tissues, and the three most significantly down-regulated genes (PRKCG, CAMK2A, and HTR2A) had lower expression in tumor tissues." (PMID 41331166, 2025). "The antitumor effects of CBD appear to be mediated by transient receptor potential cation channels (TRPVs) in endometrial cancer, glioma, bladder cancer, and myeloma, with TRPV1, TRPV2, and TRPV4 playing key roles in activating apoptosis." (PMID 40006844, 2025). "Recently, ROCK1 is found as a novel Rac1 effector, and TRPV4 targets the AKT for phosphorylation, promotes migration and invasion through AKT/Rac1 signaling in glioma." (PMID 37369706, 2023). "CBDis a well-tolerated, nonpsychoactive phytocannabinoid thatexhibits antitumor activity against GBM and glioma stem-like cells.This is achieved through mechanisms such as inducing oxidative stress,activating caspases, modulating ERK and TRPV2/TRPV4 signaling, andsuppressing NF-κB and Id1." (PMID 41288593, 2026). "Notably, we observed among the articles included in this study that CBD was able to interact mainly with TRPVS receptors, as in endometrial cancer (TRPV1), glioma (TRPV2 and TRPV4), bladder cancer (TRPV2), and myeloma (TRPV)." (PMID 40006844, 2025). "Similar to TRPV4, TRPC1 is also increased in GBM patients and is involved in glioma cell proliferation and migration via regulating chemotaxis at the leading edge of migratory glioma cells." (PMID 36497413, 2022). "It is worth mentioning that although the expression of TRPV4 in different grades of glioma did not meet the inclusion criteria (p > 0.05), the difference in expression in OS time was significant." (PMID 35625048, 2022).
glioma (continued). "Indeed, it has been demonstrated that TRPV4-mediated Ca2+ influx upon stimulation with the selective agonist GSK1016790 A, is able to promote cell migration of glioma cells, a similar mechanism previously reported in breast cancer." (PMID 33928077, 2021). "Furthermore, we investigated the correlation between TRPV4 and the progression-free survival (PFS) rate of patients in the TCGA-glioma dataset." (PMID 32843668, 2020). "Therefore, we concluded that TRPV4 expression was elevated in HGG and had a negative correlation with the prognosis of patients with glioma, especially GBM." (PMID 32843668, 2020).
Pruritus (23 papers, 2016 to 2026). Pruritus is an itch or a sensation that makes a person want to scratch. "In this study, we therefore aimed to investigate the putative interactions between TSLP and TRPV4, specifically in the keratinocytes, peripheral sensory neurons, and mast cells, for elucidating the mechanisms underlying dry skin-induced pruritus." (PMID 34925342, 2021). "Collectively, our findings suggested that although LPS is not a potent pruritogen, it might sensitize TRPV4 channel to aggravate itch, driving us to explore the underlying mechanisms of LPS‐enhancing TRPV4‐mediated acute pruritus." (PMID 38957035, 2024). "Our results argue that cutaneous disease activity, TNF-α, and IL-6 might play a central role in DM-associated itch, while TRPV4 plays a central role in tissue regeneration." (PMID 37250649, 2023). "Considering TRPV4 is also involved in the transduction of itch sensation, this provides a hint that TRPV4 may play a significant part in the process of LPS infection‐associated itch in mice, prompting us to investigate the role of the implication of LPS‐TRPV4 interaction in itch signal transduction." (PMID 38957035, 2024). "Research using mouse models indicates that TRPV4 in KCs plays a role in both acute and chronic pruritus responses." (PMID 41596464, 2026). "Within this integrated microenvironment, specific TRP channels, notably TRPA1, TRPV1, TRPV3, and TRPV4, exhibit a remarkable ability to simultaneously influence both fibrotic and pruritus-related signaling pathways." (PMID 41596464, 2026). "Beyond its role in pruritus, TRPV4 activity influences keratinocyte differentiation and skin barrier activity." (PMID 41301800, 2025). "In ethological testing, the six molecules induced analogous mechanical allodynia in a TRPV4-dependent manner and triggered acute itch in a dose-dependent manner." (PMID 40325821, 2025). "Excessive ROS accumulation can further target the TRPV4 ion receptor channels, and TRPV4 in HaCaT cells is directly involved in the development of pruritus." (PMID 40382359, 2025). "Previous studies have shown that transient receptor potential vanilloid 4 (TRPV4), a calcium-permeable ion channel protein, plays an important role in Th2 immune response and pruritus in AD." (PMID 41301800, 2025). "It is currently unclear which types of TRPV4‐expressing cells contribute to LPS‐induced augmented itch." (PMID 38957035, 2024). "In numerous mouse disease models (psoriasis, allergic contact dermatitis and dry skin) and models using pruritus-inducing substances and TRPV4 agonists, a role for TRPV4 in itch induction has been confirmed." (PMID 37555911, 2023). "While this generates a positive feedback loop of enhanced TSLP production, TSLP can also activate the innervated peripheral sensory neurons through TSLPR and TRPV4, thereby producing electrical signals for the onset of pruritus." (PMID 34925342, 2021). "Together, these studies suggest that both skin keratinocytes and sensory neurons are important locales where TRPV4 differentially regulates various forms of acute itch." (PMID 34299208, 2021). "The present study suggests the importance of TSLP and TRPV4 in dry skin conditions and identified potential molecular targets for dry skin-induced pruritus." (PMID 34925342, 2021). "AEW-induced dry skin itch and SADBE-induced itch in mice both require TRPV4; therefore, the antagonist of TRPV4 alleviate scratching in these models." (PMID 34276687, 2021). "Although TRPV1 and TRPA1 are the major TRP ion channels that are directly involved in various types of pruritus, increasing evidence suggests that TRPV4 also plays an essential role in pruritus." (PMID 34925342, 2021). "Does LPC-triggered itch involve TRPV4 in skin keratinocytes, given the propruritic role of TRPV4 in these cells?" (PMID 33819485, 2021). "Overall, the results demonstrated that the cutaneous neuroimmune interactions of TSLP and TRPV4 play pivotal roles in dry skin-induced pruritus." (PMID 34925342, 2021).
Pruritus (continued). "The first association between TRPV4 and the itch sensation was initially determined in burn scars from patients with post-burn pruritus where an increase in TRPV4 expression was observed." (PMID 32481620, 2020). "Interestingly, the activation of transient receptor potential cation channel subfamily V member 4 (TRPV4) by TSLP seems to be related to pruritus occurrence on dry skin." (PMID 38541978, 2024). "Additionally, TRPV4 expressed in mouse and human skin is involved in the mechanism of pruritus in rosacea." (PMID 38957035, 2024). "In summary, we found that LPS could not directly activate TRPV4, but enhanced the GSK101‐evoked acute itch by sensitizing TRPV4, and this sensitization relied on LPS‐TLR4‐PI3K‐AKT signalling pathway." (PMID 38957035, 2024). "This study provides a new research direction for the mechanism of TRPV4-mediated PS pruritus." (PMID 37705977, 2023). "For example, lysophosphatidylcholine (LPC) activates TRPV4, leading to the release of microRNA-146a that causes itch by targeting sensory neurons, matching the elevated concentrations of both LPC and microRNA-146a in cholestatic itch patients." (PMID 36385768, 2022). "Serotonin (5-HT)-induced pruritus has also been shown to involve TRPV4 signaling." (PMID 36613861, 2022). "Other TRP channels, such as TRPC4 and TRPV4, have also been reported to play a role in pruritus." (PMID 36385768, 2022). "Recent studies suggest that TRPV4 may play a role in these dermatologic conditions as well as in other forms of chronic pruritus." (PMID 36613861, 2022). "In addition, a significant increase in Trpv4 mRNA was detected in burn scars of patients with pruritus and the level of Trpv4 mRNA was positively correlated with the intensity of pruritus." (PMID 34299208, 2021). "Although CQ-induced itch has been reported as increased, decreased, or unchanged in Trpv4 KOs, we found that it was not significantly altered in either sensory neuron- or skin keratinocyte-Trpv4 cKOs." (PMID 34299208, 2021). "Moreover, our results revealed that the mRNA expression levels of Trpa1, Trpv1, and Trpv4 were significantly increased in the DRGs of the dry skin-induced chronic itch model." (PMID 35095413, 2021). "However, the relationship between TSLP and TRPV4 in dry skin-induced pruritus remains to be investigated." (PMID 34925342, 2021). "Interestingly, chloroquine induces itch in a fashion that is dependent on TRPV4 expression in DRG neurons, where the TRPV1 channel is also expressed." (PMID 32481620, 2020). "This means that TRPV4 ion channels in skin keratinocytes powerfully control organismal itch-related scratching behavior by converting the epidermal keratinocyte into an itch-generator cell that directly or indirectly signals to peripheral pruriceptor sensory neurons." (PMID 26961876, 2016). "When viewing these results together with our current findings, an interesting formation of an ET-1-responsive itch circuit emerges that has its origin with ET-1-responsive keratinocytes that use TRPV4 as critical Ca2+ influx mechanism in response to ET-1 receptor-A activation." (PMID 26961876, 2016). "Furthermore, dry skin-induced pruritus was attenuated by TRPV4 selective antagonists." (PMID 36613861, 2022). "Additionally, two mouse skin itch models have strengthened the role of TRPV4 in itch production." (PMID 32481620, 2020). "Lee found that skin dryness relied on TRPV4 channels to induce TSLP production in KCs and promote pruritus." (PMID 37705977, 2023). "In this review, we discuss the role of TRP channels TRPA1, TRPV1, TRPV2, TRPV3, TRPV4, TRPM8, and TRPC3/4 in acute and chronic pruritus." (PMID 38139833, 2023). "Accordingly, mice co-injected with TRPV1 and TRPV4 antagonists showed a decrease in chloroquine induced pruritus, indicating that TRPV1 and TRPV4 cooperate in transducing pruritogenic stimuli and in producing the scratch response." (PMID 32481620, 2020).
Pruritus (continued). "It was shown that certain thermosensitive TRP channels, especially TRP vanilloid 1 (TRPV1), TRPV3, TRPV4 and TRP ankyrin 1 (TRPA1), have important roles in the pathogenesis of pruritus as well as pain." (PMID 29140280, 2017). "In our previous study, we evaluated the clinical and histopathological characteristics of patients with post-burn pruritus and discovered increased expression of TRPV3, TRPV4 and TRPA1." (PMID 29140280, 2017). "We documented that increasing concentrations of small-molecule-selective TRPV4 activator, GSK101, evoked itch behavior with increasing frequency." (PMID 26961876, 2016). "The activation of TRPV4 in KCs results in calcium influx that initiates ERK phosphorylation through the MEK/ERK/MAPK pathway, quickly converting KCs into active cells that promote pruritus." (PMID 41596464, 2026). "Like TRPV3, TRPV4 mRNA expression was increased in burn patients with pruritus compared to burn patients without pruritus and normal skin, and is positively correlated with the intensity of pruritus." (PMID 37555911, 2023). "In addition, TRPV4 triggers TSLP release, which activates sensory neurons through TSLPR and TRPV4 in a dry skin-induced pruritus model." (PMID 35432341, 2022). "In contrast, burn scars of patients without pruritus showed lower TRPV4 expression than the former group." (PMID 32481620, 2020). "Yang found that TRPV4 mRNA expression was significantly increased in patients with burn scar pruritus and was positively correlated with pruritus intensity compared with that in patients without scar pruritus." (PMID 37705977, 2023). "The role of TRPV4 was described in both allergic and non-allergic pruritus by mediating 5-HT release from mast cells and keratinocytes, respectively, and its activation in keratinocytes results in ET-1 release, as well, which is thought to play a role in sunburn-associated pain." (PMID 33130130, 2021).
heart failure (22 papers, 2016 to 2026). Inability of the heart to pump blood at an adequate rate to meet tissue metabolic requirements. "Our results indicate that TRPV4 may be implicated in pathological cardiac hypertrophy and heart failure." (PMID 35731090, 2022). "Mechanotransduction and Heart Failure: Mechanosensitive TRP channels (e.g., TRPC6, TRPM7, TRPV4) are activated under pathological stretch, making them promising targets in heart failure." (PMID 40313873, 2025). "TRPV4 expression was assessed in heart failure (HF) models, induced by isoproterenol infusion or transverse aortic constriction, and in exercise-induced adaptive remodeling models." (PMID 38338818, 2024). "Despite the convincing evidence in animal models, it must be noted that TRPV4 expression regulation in human heart failure remains uncertain, with some studies showing increased expression levels, while others found no significant regulation." (PMID 37371124, 2023). "Recently, a promising clinical antagonist GSK2193874, which possesses high TRPV4 affinity, has been shown to efficiently prevent and treat lung edema in heart failure models and congestive heart failure." (PMID 37371124, 2023). "Matrix stretching can activate transient receptor potential cation channel V4 (TRPV4), and preclinical animal studies have successfully shown that oral TRPV4 channel inhibitors can prevent pulmonary edema relevant to heart failure." (PMID 36978927, 2023). "Taken together, these findings are promising and identify TRPV4 as a potential therapeutic target to attenuate cardiac fibrosis, cardiac dysfunction and arrhythmias in heart failure and myocardial infarction." (PMID 37371124, 2023). "We showed that TRPV4 activation promoted the development of pathological cardiac hypertrophy and heart failure." (PMID 35731090, 2022). "TRPV4 antagonism provides an exploitable therapeutic advantage for the treatment of cardiac hypertrophy and subsequent heart failure." (PMID 35731090, 2022). "In this study, we characterized the functional role of TRPV4 in pressure-induced cardiac hypertrophy and heart failure." (PMID 35731090, 2022). "The TRPV4 antagonist GSK2193874 mitigates the increases in lung weight after heart failure and TRPV4 inhibition or genetic deletion suppresses pulmonary inflammation and improved pulmonary function in the HCl-and Cl2- induced injury model." (PMID 33981725, 2021). "A clinical trial of TRPV4 blockers and their promising roles in the treatment of dyspnea and pulmonary edema in heart failure and acute decompensated heart failure cases is currently finished in phase 1 stage." (PMID 32256338, 2020). "Furthermore, TRPV4 antagonists have shown therapeutic potential in experiment animal models for a range of conditions, including heart failure, edema, pain, gastrointestinal disorders, lung diseases, and various cancers." (PMID 38188686, 2023). "TRPV4’s expression and function in human heart failure will require further investigations." (PMID 37371124, 2023). "In addition, a potent and selective TRPV4 inhibitor recently revealed a positive efficacy trend in a Phase 2a trial in patients with heart failure." (PMID 35731090, 2022). "In addition, TRPV4 is a critical mediator of pressure-induced damage related to ventilator-induced lung injury, infarction, and heart failure." (PMID 33981725, 2021). "Similarly, another single-center study designed to estimate the effects of GSK2798745, a novel TRPV4 inhibitor, on pulmonary gas exchange and pulmonary function in participants with heart failure has already completed a phase 2 clinical trial." (PMID 32256338, 2020). "Finally, it was recently reported that GSK2798745 is well-tolerated when this compound is systemically applied in healthy subjects and in patients with heart failure, indicating the safety and tolerability of this TRPV4 blocker (ClinicalTrials, Identifier: NCT02119260)." (PMID 32481620, 2020).
heart failure (continued). "Interestingly, a recent clinical study in patients with stable heart failure found that the novel, first-in-class TRPV4 inhibitor GSK2798745 was well tolerated, suggesting that TRPV4 blockade might be a safe target for metastatic breast cancer." (PMID 32825277, 2020). "Furthermore, the inhibition of TRPV4 by genetic deletion or antagonist GSK3874 attenuated TAC-induced cardiac hypertrophy and subsequence heart failure in vivo." (PMID 35731090, 2022). "In 2019, a study on heart failure with oral TRPV4 antagonists on humans was conducted; however, there were no reports of weight gain or loss." (PMID 36397882, 2022). "The first, study NCT02497937, aimed to assess the impact of the TRPV4 blocker GSK2798745 on pulmonary gas transfer and respiration in patients with congestive heart failure and the second trial, NCT02135861, sought to validate a novel treatment for pulmonary edema in cardiac failure." (PMID 39333347, 2025). "Recently, the TRPV4 antagonist GSK2798745 was administered to healthy volunteers and heart failure patients without any safety concern." (PMID 32708074, 2020).